FN1 (fibronectin 1)
Diseases named in the same sentence as FN1 in open-access papers (continued):
Sharing a sentence is not in itself a finding about the gene and the disease.
cancer (continued). "From our big data studies validated with independent datasets, protein-coding hub genes FN1, CD44, TIMP1, SNAI2, and SPARC were found significantly enriched in signal transduction, proteolysis, cell adhesion and proteoglycans pathways in cancer as well as the PI3K/Akt-signaling pathway." (PMID 35534592, 2022). "FN1 overexpression can trigger ER stress and facilitate lipid accumulation, while BAAT transcription in conjugation with glycine or taurine regulates cholesterol and phospholipid synthesis, favoring cancer growth." (PMID 35626705, 2022). "FN1, significantly correlated with LOX expression in GBM in the present analysis, may also promote angiogenesis in cancer by providing a ridged structure for vessel development and signaling for endothelial cell migration." (PMID 36076905, 2022). "CD44 is a cancer stem cell marker and is known to interact with OPN, FN1, and Ezrin 36-38." (PMID 34976221, 2022). "A positive correlation between FN1 and MACC1 was also observed in ten cancer types in TCGA." (PMID 36333284, 2022). "Nevertheless, THBS1, FN1, TNC, COL1, and COL4 were expressed in both stroma and cancer cells." (PMID 34121340, 2021). "Similarly, in prostate cancer it has been shown that CAF-mediated FN1 fibrillogenesis promotes CAF–cancer cell interactions and guides cancer cell migration." (PMID 33731188, 2021). "In addition, we observed upregulation of several collagens, integrins and other cell adhesion molecules, including FN1 and ALCAM, suggesting modulation of adhesive properties in cancer cells upon flow exposure." (PMID 34641959, 2021). "In a study, the expression level of cell adhesion molecules like fibronectin 1 (FN1), integrin, CD44, ICAM-1, E-cadherin, N-cadherin, and Vimentin that have previously been confirmed to have a role in invasion and metastasis in various cancers was measured." (PMID 34337048, 2021). "Incorporation of SPARC-integrin-FN1-mediated activation of AKT may be involved in activation of fibroblasts and dominant changes in ECM to help cancer cells to mobilize or invade into adjacent stroma." (PMID 33579227, 2021). "Furthermore, Spearman correlation analysis in TCGA HCC tissues revealed that MARCH6 was positively correlated with MKI67, CTNNB1, CDH2, FN1 and WNTSA, which were demonstrated as oncogene in cancer growth and metastasis." (PMID 34273954, 2021). "More specifically, therapeutic modulation of FN1, TPT1, RTN4, and FSTL1, for which knockdown has been shown to result in reduced cell proliferation and migration in cancer cells, may represent new potential therapeutic avenues for pterygia as well." (PMID 35174178, 2021). "TGFβ can induce EMT in cancer cells via upregulation of STAT3, vimentin, and FN1." (PMID 33917306, 2021). "Much like FN1, β-catenin, another important player involved in migration and invasion of cancer cells, whose expression showed no change in group transfected with sgCALM1-1." (PMID 33602237, 2021). "However, the compartmentalization of FN1 into EVs is emerging as a novel and consistent feature of several cell types including HSC, melanocytes, trophoblasts, or cancer cells but with few exceptions mechanistic and functional studies are lacking." (PMID 33816490, 2021). "The area under the curve (AUC) of FN1 expression was 0.875, higher than that of epidermal growth factor receptor (EGFR) expression (AUC = 0.756, p < 0.001), which has been regarded as a biomarker in multiple malignant carcinomas." (PMID 34746236, 2021). "FN1 was significantly overexpressed in HNSCCs compared with normal para-carcinoma tissues on the basis of TCGA database and in our 20 matched pairs of clinical samples." (PMID 34746236, 2021). "Furthermore, Twist1 expression positively correlates with EMT genes (CDH1, OCLN, TJP1, CDH2, FN1, SNAI1 and VIM) in various cancers." (PMID 32337580, 2020).
cancer (continued). "Correlational analysis of clinical OSCC datasets with TGFβ axis differentially expressed genes revealed that the summed expression of FN1, TGFB2, TGFBR2, and TGFBI, dubbed as the CAF index, is a powerful predictor in dichotomized survival analysis for patients of diverse cancer subtypes." (PMID 32605311, 2020). "Altogether, our study reveals novel molecular mechanisms by which FN1 may regulate CTC migration, and further highlights the importance of FN1 in cancer progression and metastasis." (PMID 32630254, 2020). "Our work is noteworthy in that it is one of the few in the FN1 oncogenic field to highlight FN1’s active regulation of molecules to impact cancer cell migration rather than focus on its connecting role in the ECM." (PMID 32630254, 2020). "FN1 can induce abnormal expression of some MMPs, such as MMP9/MMP2 and promote proliferation, migration, and invasion in thyroid and gastric cancers." (PMID 30886783, 2019). "The FN1 and ZNF737 genes are relatively well-known cancer-related genes." (PMID 30911020, 2019). "Moreover, the gene microarray indicated knockdown of PSMC2 notably changed a number of genes, especially some cancer related genes including ITGA6, FN1, CCND1, CCNE2 and TGFβR2, and whose expression changes were further confirmed by western blotting." (PMID 27888613, 2017). "It is possible that a lack of continual stimulation of stroma by cancer cells in culture explains the normal levels of FN1 we have seen in the diseased stromal cells; but this is an open question requiring additional investigations." (PMID 26934553, 2016). "In accordance with FN1 and TJP1 roles in aggressive metastatic cancer cells, the former promotes and the latter suppresses the cancer cell aggression, western blotting demonstrated that FN1 was positively regulated and TJP1 was negatively regulated by TFCP2 in human HCC cells." (PMID 25609232, 2015). "ATF3 up-regulates the genes TWIST1, fibronectin (FN)-1, SNAIL and SLUG in MCF10A cancer cells." (PMID 26537518, 2015). "Notably, two cassette exons that were altered significantly in more than four cancer types were also found among these consistently altered cassette exons; exon 9 of the gene FBLN2, and the EDB exon of the gene FN1." (PMID 25908786, 2015). "Our RNA-Seq data shows that expression of FN1, MSN and MMP9, which belongs to “Proteoglycans in cancer” gene list and are targets of down-regulated miRNAs, was up-regulated in 10 of 13 tissue samples (on average, 6.83, 2.43 and 21.89 folds, respectively, compared to adjacent normal)." (PMID 25126847, 2014). "The expression ratios of FN1 in the cancer to adjacent tissues in samples without HBV integration also varied greatly." (PMID 23236287, 2012). "In addition, strong A4B1 interactions with FN1, VCAM1 and other ligands are seen with fibroblasts in P5-1, P6-1, and P7-1, and ESC in P6-1; A4B1 receptors have been proposed to target therapy in inflammatory disorders and cancer." (PMID 38328306, 2023). "Moreover, the expression of CDKN1A and senescence gene FN1 with the lack of expression of PCNA can trigger the G2 arrest or the stress-induced premature senescence (SIPS) found in a previous cancer study." (PMID 38328306, 2023). "In addition, we also analyzed the correlation between NUTF2 and the epithelial–mesenchymal transition (EMT) markers, Vimentin (VIM), TWIST1, Snail1 (SNAI1), Snail2 (SNAI2), Fibronectin 1 (FN1), and N‐cadherin (CDH2), which were widely accepted to be involved in cancer metastasis." (PMID 35155261, 2022). "However, in the case of combined Selumetinib- and Trametinib-resistant cancers, FN1 and CD44 were down-regulated; TIMP1 and SNAI2 were down-regulated only in Selumetinib-resistant ones; while SPARC was down-regulated in the case of Trametinib-resistant cancer." (PMID 35534592, 2022). "Furthermore, FN1 could be an independent prognostic factor for HNSCC patients, which was consistent with previous studies in other malignant tumors." (PMID 34746236, 2021).
cancer (continued). "In addition, a potential role of HK2 in altering FN1 expression in cancer cells has not been reported." (PMID 34758823, 2021). "Consequently, we can conclude that FN1-dependent enhanced migration of CTCs requires downstream signaling through either ITGB1 or SLUG and that FN1 regulation of ITGB1 and SLUG may have important implications for cancer progression and metastasis." (PMID 32630254, 2020). "Therefore, markers of EMT, such as vimentin, FN1, twist family bHLH transcription factor 1 (TWIST1), snail family transcriptional repressor 1 (SNAI1) and 2 (SNAI2, best known as SLUG) can be used to detect cancer dormancy." (PMID 33193295, 2020). "Moreover, upregulation of the Fn1, Mmp2, and Snai1 mRNAs, which are hallmarks of tube-forming growth in PDAC, was demonstrated in a mouse model of carcinogenesis showing rapid progression because of the aggressive invasion of tube-forming cancer." (PMID 31375695, 2019). "Further analysis suggested that modulation of angiogenesis-related genes (including ANGPTL4, FN1, HSPG2, SRPX2, KLK5, L1CAM, Prr22, FOXJ1, IL24, and TRIM54) potentially contributes to anlotinib resistance, as anlotinib is a multi-targeted anti-angiogenesis drug for cancer therapy." (PMID 31572680, 2019). "Interestingly, similar to FN1 and FN16, AKBA, and in particular, β-ABA, showed higher toxicity against cancer cells compared to PBMC, suggesting selectivity against cancer cells." (PMID 31581678, 2019). "FN1-driver gene fusions were reported in other rare tumors such as FN1-ALK and FN1-FGFR1 and FN1 expression might be related with driver event for cancer, but further study is required to evaluate the functional significance of such HBV-FN1 fusions." (PMID 29861854, 2018). "Moreover, TGFβ from cancer cells induces the expression of MMP1 and fibronectin (FN1) in CAFs." (PMID 27586372, 2017). "This study suggests that Fibronectin 1/CXCL9 dosage in serum could screen a significant rate of BC, including ER-negative, and that differential gene expression analysis is a good approach to select candidate biomarkers to set up blood assays cancer screening." (PMID 20068563, 2010). "However, as a subgroup of CSC, L3 does not express genes related to cancer dormancy (FN1, CD47, and THBS1); therefore, L3 is a smaller, independent cluster that expresses high levels of stem cell markers while lacking the expression of cancer dormancy marker genes." (PMID 37858183, 2023). "Interestingly, it has also been demonstrated that SOX2 overexpression induces fibronectin 1 (FN1) through the PI3K/AKT/NF-kB pathway in cancer; therefore, it is not excluded that this occurrence could be valid also for BC." (PMID 37238229, 2023). "Therefore, FN1 and VTN might also be translatable to other cancer types or disease settings." (PMID 35477343, 2022). "Patients who did not respond to immunotherapy had cancer tissues with elevated BMP6 and FN1 expression, in contrast to those who responded, where CD274, HOXB5, and PPIL3 were more expressed." (PMID 40642086, 2025). "Furthermore, correlation of FN1 3′-UTR with metastasis-related molecular mechanisms and the more aggressive nature of FN1 3′-UTR compared with the FN1 protein suggest that FN1 3′-UTR might be a better target for inhibiting cancer development than the FN1 protein." (PMID 37771777, 2023). "The region of cancer tissue positive for SPARC also showed FN1 expression in the stromal area, and the region without SPARC expression also lacked FN1 expression the stromal area." (PMID 33579227, 2021). "This was consistent with previous studies indicating that FN1 is frequently targeted for HBV integration at the transcript level, but that it is not a cancer driver gene." (PMID 29212479, 2017). "PTGS2, FN1, CXCL9, CXCL10, ZIC2 e OVOL1 podem desempenhar alguns papéis no carcinoma nasofaríngeo." (PMID 27765529, 2017).
cancer (continued). "Importantly, in this study, we found that although disseminated cancer cell clusters displaying highly expressed CD44 were mobile and invasive, the cell-cell junction molecules were not lost (e.g., Msn, Fn1)." (PMID 35680853, 2022). "Although FN1 was not identified as key genes in our study because it did not affect 231-BR cell migration in wound healing assay, its possible role in BCBM through Proteoglycans in cancer signaling pathway should not be ignored." (PMID 35096583, 2021). "ZIC2 e OVOL1 podem funcionar no carcinoma nasofaríngeo almejando-se de maneira significativa os genes suprarregulados (como o PTGS2, FN1, CXCL9 e CXCL10) na rede reguladora de fator de transcrição - genes diferencialmente expressos (p.ex., ZIC2→PTGS2 e OVOL1→CXCL10)." (PMID 27765529, 2017). "Our results suggest that radiation-induced increases of FN1, CTSD, GSN, and MRC2 may play radioresistant and negative roles in cancer therapy." (PMID 26056562, 2015).
infection (65 papers, 2008 to 2025). The state of being infected such as from the introduction of a foreign agent such as serum, vaccine, antigenic substance or organism. "Finally, protein–protein interaction analysis identified three primary proteins (ICAM1, TLR2, and FN1) associated with microbial infections mediating pro-inflammation, controlling infection, and facilitating microbial elimination." (PMID 37233676, 2023). "This might be attributable to the fact that after half a year of SARS-CoV2 infection, although the profibrotic effect might have gradually weakened, the increase in FN1 levels caused by early infection might require more time to return to normalcy." (PMID 35288537, 2022). "In muscle tissue, infection significantly upregulated FN1 expression by 379-fold, suggesting substantial fibrosis and extracellular matrix remodeling." (PMID 41026274, 2025). "Analysis of pro-tumorigenic markers revealed that 4T1 upregulated expression of epithelial–mesenchymal transition (EMT)-related Fn1 and Timp1 in macrophages, but infection reduced it." (PMID 40547518, 2025). "When inspecting the protein-protein association network for the HFF adhesome (from the STRING database), the strongest differences between Δvhs infection and WT infection were observed in the subnetwork around FN1 and integrin subunits." (PMID 33148793, 2021). "Transcriptome group 1 (CAMP, CD14, FN1, TREM1) encodes for proteins that relate to acute response to infection, in particular to the LPS/TLR4 signaling pathway." (PMID 32325790, 2020). "The Euclidean distances between protein aggregation profiles indicated that, while ITGB1 and collagen (COL1A1) or fibronectin (FN1) became gradually distant during infection, ITGB1 and CD63 became closer." (PMID 32041945, 2020). "Through the time course study, the strongest suppression of FN1 transcription and secreted Fn expression was observed at 30 min and 2 h-post infection, respectively." (PMID 28407745, 2017). "Reduction of the expression of FN1 was observed when macrophages were infected by strain 12,598 and the strongest reduction was observed at 30 min post-infection." (PMID 28407745, 2017). "Herein, we revealed that infection with miR-122-expressing lentiviruses significantly enhanced miR-122 levels and meanwhile reduced the amount of FN1 and collagen fibrils in the livers of CCl4-treated mice." (PMID 25909171, 2015). "Here, we considered that intrahepatic Fn1+Ifitm3+ classical monocytes may be a maker immune cell during the inflammation or infection after LT." (PMID 38143768, 2023). "Interestingly, WT microglia dramatically increased Lpl, Fn1 and Cd36 expression after infection, whereas Trem2 ablation resulted in the complete failure to upregulate these genes in microglia." (PMID 36333761, 2022). "Transcriptional level of FN1 in macrophages upon infection was also determined by RT-PCR." (PMID 28407745, 2017). "Only approximately 10% of the macrophages had been killed following to S. aureus infection (4 h post-infection) but a five-fold reduction of the Fn secretion was already observed 2 h post-infection, as well as the downregulation of the FN1 transcription was observed." (PMID 28407745, 2017). "The analysis of the whole dataset at T1 showed only two significant differences after the Bonferroni correction, both of them having the lower infection dose: HAN1 vs N1 (p<0.05), with an increase of NcU/bee upon treatment and FN1 vs N1 (p<0.01)." (PMID 36637793, 2024). "FN1 also binds to HIV-1 gp120, which has been shown to enhance complement interaction and infection of primary CD4 + T-cells." (PMID 39632834, 2024). "In contrast, other Wnt-induced targets (CCND1, FN1, MCT1, MYC) were significantly downregulated by the infection." (PMID 38584257, 2024). "Expression of Lpl, Fn1 and Cd36 were downregulated in both microglia and BMDM from Trem2−/− mice relative to WT mice overtime after infection." (PMID 36333761, 2022).
infection (continued). "The expression of CD11b, CD4, CD14, and CD68 for M0; IL-6, HLA/DRA, and CXCL10 for M21, and IL-10, CD163, fibronectin-1 or FN1, and CCL17 was evaluated by qPCR at 2 and 24 h after infection." (PMID 35889103, 2022). "We observed increased expression of the CD14 and FN1 genes following BCG, H37Ra and H37Rv infection, confirming their critical role in M.tb infection." (PMID 34632719, 2021). "Infection significantly increased the expression of ACE2, TMPRSS2, ADAM17, TGFB1, CTGF, VEGFA and FN1 but resulted in trends towards decreases in TIMP3 (p = 0.083) and AGF (p = 0.086) in A549 cells compared to control cells." (PMID 32664949, 2020). "Following infection, heterophils decreased ALB and FN1, and released MMP9 to enable their translocation to the site of infection." (PMID 28623956, 2017). "Heterophils decreased ALB and FN1, and released MMP9 to enable their translocation to the site of infection." (PMID 28623956, 2017). "Notably, Fibronectin 1 (FN1), Toll-like receptor 2 (TLR2), and ICAM1 were involved in all three infection categories." (PMID 37233676, 2023). "Genes coding for the ECM proteins fibronectin (fn1) and decorin (dcn) were highly expressed in the dura mater; however, expression levels were not altered in response to infection." (PMID 33524035, 2021). "The expression of FN1 by macrophages in uninfected samples suggests the coordination of fibroblast activity involved in tissue healing that is not present during dormant or active infection." (PMID 39563367, 2024). "While FN1 expression in M1 and M2 macrophages appeared to be a hallmark of uninfected tissue and expression of HLAs in both macrophage subtypes and myeloid dendritic cells appeared to be a hallmark of infection, despite none of the MPS lineages distinguishing dormant from active infection." (PMID 39563367, 2024). "Eight of them (FN1, ALB, CTSL1, OTFB, LYZ, CATHL1, MMP9, LECT2) did not change their expression at the level of transcription and transcripts of 3 of them (RSFR, LYG2, CSTC) even increased following infection." (PMID 28623956, 2017).
kidney disease (13 papers, 2017 to 2025). "Transcript levels of Col1a1, Col3a, and Fn1 were higher in the kidney disease models, but they were lower in Acss2–/– mice with kidney injury." (PMID 38051585, 2023). "The indirect evidence partly demonstrated that FN1 and POSTN are strongly associated with many different heart and kidney diseases, thereby influencing the pathogenesis of CRS." (PMID 35133974, 2022). "The transcriptome sequencing data of humans obtained from the GEO revealed that FN1 and POSTN were both significantly associated with many different heart and kidney diseases." (PMID 35133974, 2022). "Therefore, FN1 is involved in kidney diseases and overexpressed during aging and considered a pro-longevity gene in mice." (PMID 40809316, 2025). "Subsequent comprehensive genetic testing, which was initially not conducted because the patient’s parents did not have a history of kidney disease, identified a known disease-causing variant in the FN1 gene, indicating a de novo variant." (PMID 38254040, 2024). "The vital roles of FN1 and POSTN in heart and kidney disease have previously been reported." (PMID 35133974, 2022).